HLA-B (major histocompatibility complex, class I, B)
Diseases named in the same sentence as HLA-B in open-access papers (continued):
Sharing a sentence is not in itself a finding about the gene and the disease.
agranulocytosis (15 papers, 2015 to 2025). "The HLA-DQB1*05:02 allele has been strongly linked to clozapine-induced agranulocytosis, while HLA-B*59:01 shows association with myocarditis risk, particularly in Asian populations." (PMID 41050417, 2025). "Although pharmacogenetic testing was not performed in this case, genome-wide studies have identified associations between metamizole-induced agranulocytosis and polymorphisms in HLA-B*27:05, NAT2, and cytochrome P450 isoenzymes." (PMID 41267696, 2025). "Certain HLA alleles, such as HLA-DRB1*04:02, HLA-DPB1*05:02, HLA-DQB1 (126Q), HLA-B (158T), and HLA-B*59:01, have been reported to be associated with clozapine-induced agranulocytosis." (PMID 38516266, 2024). "Among white Europeans, carriers of the HLA-B*27:05 gene or certain single nucleotide polymorphisms (SNPs) on chromosome 6 have an increased risk of thyrostatic-induced agranulocytosis." (PMID 34483939, 2021). "Patients carrying the “A” allele of SNP rs1811197 or the HLA-B*38:02 allele more easily develop severe agranulocytosis." (PMID 28931918, 2017). "In the present study, agranulocytosis occurred in all subjects carrying the HLA-B 27*05 allele, indicating a strong association of HLA-B*27:05 with the susceptibility of our population to ATD-induced agranulocytosis." (PMID 28931918, 2017). "In White European populations, ATD-induced agranulocytosis is associated with the HLA-B*27:05 allele and with a set of SNPs located on chromosome 623." (PMID 28931918, 2017). "All subjects carrying the HLA-B*27:05 allele had agranulocytosis." (PMID 28931918, 2017). "For instance, HLA-B*38:02 and HLA-DRB*108:03 have been implicated in antithyroid drug-induced agranulocytosis, and HLA-B*57:01 is strongly associated with abacavir hypersensitivity." (PMID 40558808, 2025). "For example, two alleles, HLA-B*38:02 and HLA-DRB1*08:03, are strongly associated with the adverse side effect of induced agranulocytosis when starting anti-thyroid medication." (PMID 37033561, 2023). "The human leukocyte antigen (HLA) region has been associated with genetic susceptibility to clozapine-induced agranulocytosis (single amino acid changes in HLA-DQB1 (126Q) and HLA-B (158T))." (PMID 29298994, 2019). "Our findings support the association between genetic variations of HLA-B and HLA-DRB1 with ATD-induced agranulocytosis in a Han population from northern China." (PMID 28931918, 2017). "HLA-B*27:05 (P = 1.10 × 10−4), HLA-B*38:02 (P = 2.41 × 10−4) and HLA-DRB1*08:03 (P = 1.57 × 10−3) were susceptibility HLA variants for ATD-induced agranulocytosis." (PMID 28931918, 2017). "HLA-B*38:02 was present in 25.92% of patients with agranulocytosis but was present in only 4.4% of controls with GD with an odds ratio (OR) of 7.525 (95% confidence interval, CI = 2.294–24.68) for allele carriers compared with non-carriers." (PMID 28931918, 2017). "Direct HLA genotyping was used to detect HLA variants (HLA-B and HLA -DRB1) in 29 patients with ATD-induced agranulocytosis and in 140 controls with GD." (PMID 28931918, 2017). "Our findings are in line with the Hong Kong GWAS that the associations of HLA-B*38:02, HLA-DRB1*08:03, rs2596487 and rs1811197 with ATD-induced agranulocytosis become even stronger in patients with agranulocytosis caused only by MMI." (PMID 28931918, 2017). "HLA-B*27:05 (P = 1.10 × 10−4), HLA-B*38:02 (P = 2.41 × 10−4) and HLA-DRB1*08:03(P = 1.57 × 10−3) were significantly associated with ATD-induced agranulocytosis after adjusting with Bonferroni’s correction (P < 3.57 × 10−3)." (PMID 28931918, 2017). "The HLA-B*38:02 allele and single nucleotide polymorphisms (SNPs) in the HLA region were also associated with an increased risk of ATD-induced agranulocytosis in Taiwan and Hong Kong populations." (PMID 28931918, 2017). "The associations of HLA-B*27:05, HLA-DRB1*08:03 and 5 SNPs (rs2596487, rs116869525, rs2228391, rs1811197 and rs4349859) with agranulocytosis were still significant in the female patients." (PMID 28931918, 2017).
agranulocytosis (continued). "Furthermore, our previous analysis found that pretreatment HLA‐B*59:01 screening for clozapine was cost‐effective and beneficial for reducing the incidences of neutropenia and agranulocytosis in the Japanese population." (PMID 41282954, 2025). "The occurrence of clozapine-induced agranulocytosis is associated with older age and the presence of certain HLA gene variants (e.g. HLA-B38, DRB1*0402, DRB4*0101, DQB1*0302, HLA-DQB1, HLA-B, which could explain regional incidence differences." (PMID 34483939, 2021). "When we considered medication type (MMI or PTU), the associations of two HLA alleles (HLA-B*38:02 and HLA-DRB1*08:03) and 2 SNPs (rs2596487 and rs1811197) with agranulocytosis were strengthened when patients with PTU-induced agranulocytosis were removed from the analysis." (PMID 28931918, 2017). "We evaluated the associations of genetic variants at the HLA-B and HLA-DRB1 loci and 32 candidate single nucleotide polymorphisms (SNPs) with agranulocytosis in 29 patients with ATD-induced agranulocytosis and in 140 patients with Graves’ disease (GD) as controls." (PMID 28931918, 2017). "In conclusion, HLA-B*27:05, HLA-B*38:02, HLA-DRB1 *08:03 and other SNPs within chromosome 6 are associated with the susceptibility of a Chinese Han population from northern China to ATD-induced agranulocytosis." (PMID 28931918, 2017). "In the previous GWAS from Hong Kong, HLA-B*38:02:01 was associated with CMZ/MMI-induced agranulocytosis but not with PTU-induced agranulocytosis." (PMID 28931918, 2017). "Combining HLA-DQB1 with HLA-B epitope testing increased the sensitivity for CIA prediction to 41% (CI 95%: 31–51%) and showed a 30% reduction in the lower risk group (a reduction in CIA incidence from 0.7% to <0.5%), which approximates the agranulocytosis risk of other antipsychotics." (PMID 29298994, 2019). "Another 4 HLA alleles (HLA-B*38:02, HLA-B*27:05, HLA-DRB1*01:01 and HLA-DRB1*04:02) with frequencies less than 5% were also included in the analysis because of significant associations with drug-induced agranulocytosis that have been reported in the literatures." (PMID 28931918, 2017). "HLA-B*27:05 was only detected in 18.5% of patients with agranulocytosis but not in the controls with GD, with an odds ratio (OR) of 66.24 (95% confidence interval, [CI] = 3.54–1239.66) for allele carriers compared with non-carriers." (PMID 28931918, 2017). "Neither of the 2 PTU-induced agranulocytosis cases carried HLA-B*38:02 or HLA-DRB1*08:03." (PMID 28931918, 2017).
breast carcinoma (15 papers, 2009 to 2025). "A study have indicated that the expression of HLA-B is associated with the survival and recurrence rates of breast cancer patients." (PMID 39471412, 2024). "The association between HLA-B*35:03 and early-stage breast cancer showed the largest effect size after additional adjustments for study and breast cancer risk factors (OR = 0.60, P = 0.040)." (PMID 35543923, 2022). "rs1108842 in gene GNL3, rs3785181 in gene GAS11, rs879882 in gene POU5F1 and rs2523608 in gene HLA-B are reported to have a high probable association with tumor or breast cancer." (PMID 30072632, 2018). "HLA-B has been previously demonstrated to have significant immunogenic involvement in breast cancer by supporting multiple downstream immunogenic pathways." (PMID 36960071, 2023). "B4GALNT2 may promote the proliferation and metastasis of breast cancer cells by interacting with HLA-B protein." (PMID 34589428, 2021). "This study developed a signature featuring 8 OARGs (HLA-B, RBBP8, SPRY4, WT1, WWOX, UPRT, PELO, ZNF208) and determined its prognostic and functional implications in breast cancer patients." (PMID 36960071, 2023). "For example, synergism has been shown between peptide-presenting HLA-B and the peptidase ERAP1 in breast cancer." (PMID 33901204, 2021). "Infusion of expanded TIL targeting four neoantigens across HLA-B, -C and -DRB1 restrictions induced a complete response in a breast cancer patient refractory to chemotherapy, ongoing for >22 months." (PMID 34439399, 2021). "The most frequently repeated neoepitope for HLA-B*15:03, KQMNDARHG, was found most often in breast carcinoma patients." (PMID 29653567, 2018). "After 24-h treatment with IFN-γ, the relative levels of HLA-A, HLA-B and HLA-C mRNA in SKBR3 breast cancer cells were dose dependently increased in all groups treated with different concentrations of IFN-γ compared with the control group with statistical significance (p < .05)." (PMID 40596738, 2025). "HLA-B, a major histocompatibility complex (MHC) class I molecule, is involved in immunosurveillance against tumors, and its expression is correlated with the invasiveness and prognosis of breast cancer." (PMID 37929934, 2023). "Interestingly, we observed that one set of proteins was identified more frequently, with HLA-A, HLA-B, A2M, ACTB, ALDOA, ANXA2, and FN1 identified in at least 13 of 22 studies that explored the vesicular proteome in breast cancer." (PMID 37629204, 2023).
vitiligo (15 papers, 2011 to 2025). Generalized well circumscribed patches of leukoderma that are generally distributed over symmetric body locations and is due to autoimmune destruction of melanocytes. "Similar to vitiligo, these mutations are distributed in HLA‐A, HLA‐B, HLA‐C, HLA‐DQB1, and so on." (PMID 40657813, 2025). "The GEDIQLLKA peptide could bind to HLA-B*44:03, which is associated with vitiligo." (PMID 34447375, 2021). "Similar to previous studies, our findings suggest that mutations in the MHC region of vitiligo exist in multiple HLA genes, including but not limited to HLA‐A, HLA‐DRB1, HLA‐B, HLA‐C, and so on." (PMID 40657813, 2025). "Recently, we have shown positive association of HLA-A*33:01, HLA-B*44:03, and HLA-DRB1*07:01 with vitiligo patients from North India and Gujarat suggesting an autoimmune link of vitiligo in these cohorts." (PMID 23284977, 2012). "Using Beagle 4.1, we successfully imputed the SNV, CNV, two–digit and four–digit alleles of HLA genes (HLA-A, HLA-B, HLA-C, HLA-DQA1, HLA-DQB1, HLA-DPA1, HLA-DPB1, HLA-DRB1) and amino acids of 2810 vitiligo subjects (1117 cases, 1693 controls) and 2739 SLE subjects (1,693 controls and 1,046 cases)." (PMID 35082778, 2021). "In the four regression models we built, two loci in HLA-C/HLA-B and HLA-DQA2 consistently appear in all models, and more importantly, rs9468925 in HLA-C/HLA-B is reported as the top association signal in a GWAS of vitiligo in the same population of study." (PMID 22125590, 2011).
Allergy (13 papers, 2014 to 2026). An allergy is an immune response or reaction to substances that are usually not harmful. "Conduct a thorough allergy history before prescribing sulfonamide-containing eye drops and consider HLA genotyping (e.g., HLA-B*15:02) in high-risk individuals, particularly in Asian populations." (PMID 41366987, 2025). "For example, research has shown that individuals carrying the HLA-B*58:01 gene have a significantly increased risk of developing severe allergic reactions after using allopurinol." (PMID 40429170, 2025). "Therefore, performing HLA-B*58:01 gene testing on patients before using allopurinol can help predict allergy risk and avoid the use of the drug in high-risk patients." (PMID 40429170, 2025). "Interestingly, the HLA‐B*35:05 molecule has been linked to nevirapine drug allergies that led to skin rash in HIV+ patients in a cohort in Thailand." (PMID 37811811, 2024). "Additionally, the risk of allergy severity was linked to specific HLA allele genotypes, including HLA-B*46:01 (OR = 1.68, 95% CI: 1.04–2.71, p = 0.035), and HLA-DPB1*02:02 (OR = 1.95, 95% CI: 1.11–3.42, p = 0.020), when compared to their counterparts." (PMID 38137494, 2023). "Specifically, the genotype frequency of HLA-B*46:01 was significantly increased in the severe allergy group after Bonferroni correction when compared with the mild allergy group." (PMID 38137494, 2023). "Notably, the genotype frequency of HLA-B*46:01 exhibited a significant increase in the severe allergy group when compared with the mild allergy group." (PMID 38137494, 2023). "HLA-B*46:01 (OR = 1.76, 95% CI: 1.08–2.89, p = 0.02) and HLA-DPB1*02:02 (OR = 1.86, 95% CI: 1.03–3.34, p = 0.04) were significantly associated with an increased risk of allergy severity." (PMID 38137494, 2023). "Higher frequencies of HLA-B*46:01, HLA-DPB1*02:02, and HLA-DRB*03:01 were observed in the severe allergy group compared to the mild allergy group." (PMID 38137494, 2023). "The clinical implication of HLA-B-*15:02 is specifically related to SJS and not MCARs, even though both are the cutaneous manifestations of allergy." (PMID 37521485, 2023).
diabetes (13 papers, 2009 to 2025). "Some studies reported that HLA-B*39:06 could increase the risk of diabetes in combination with some low-risk haplotypes, containing DRB1*08:01, DRB1*01:01 or DRB1*16:01 alleles." (PMID 39185409, 2024). "However, its strong association with the early onset of diabetes, independently from HLA-B*39:06, supported an autonomous effect on predisposition to T1D." (PMID 39185409, 2024). "Additionally, there is recent evidence which connects specific HLA-B alleles with HLA-DR/DQ haplotypes which are known to play a relevant role in the development of diabetes." (PMID 30338375, 2018). "Therefore, the protective effect of the number of HLA-B mismatches for kidney graft function may be associated with a decreased likelihood of diabetes recurrence in the transplanted pancreas which may protect kidney graft function." (PMID 30338375, 2018). "-Earlier diabetes.- Higher prevalence.- Escape of insulin-reactive HLA-B*39:06 restricted T cells from thymus." (PMID 35498419, 2022). "The same trend was observed for T1D subjects carrying HLA-C*07:02; in contrast, we observed the opposite for carriers of the HLA-B*44:03, who had an age at onset approximately 3.5 years higher than people with diabetes without this allele." (PMID 39185409, 2024). "Besides, hypertension and diabetes are linked by CXCL8, HLA-B, and KANSL1; diabetes and obesity are linked by TRIM26 and MMP8; hypertension and obesity are linked by PLA2G7, FSTL3, STC2, and BCL2A1." (PMID 36685671, 2023). "Moreover, the HLA subtypes HLA-A*11:01, HLA-B*46:01, HLA-DPA1*01:03, and HLA-DPB1*05:01 were found to be associated with heart disease, stroke, diabetes, and hypertension among subjects with GD." (PMID 35321340, 2022). "Importantly, sQTLs also affected genes that harbor variants that cause monogenic diabetes (KCNK16, ABCC8, PDX1) or influence T2D risk (THADA, PAM) as well as genes that play a role in T1D pathogenesis (ICA1, PTPRN2, HLA-B)." (PMID 36109769, 2022). "Moreover, the HLA subtypes HLA-A*11:01, HLA-B*46:01, HLA-DPA1*01:03, and HLA-DPB1*05:01 were associated with heart disease, stroke, diabetes, and hypertension among subjects with GD." (PMID 35321340, 2022).
leukemia (13 papers, 2014 to 2025). A malignant (clonal) hematologic disorder, involving hematopoietic stem cells and characterized by the presence of primitive or atypical myeloid or lymphoid cells in the bone marrow and the blood. "Conversely, our investigation identified strong protective alleles HLA-B*49, HLA-B*40, and HLA-B*57 for pediatric leukemia (p < 0.001, p = 0.05, p < 0.04, respectively), which was similarly recognized in the U.S. population." (PMID 40508101, 2025). "To determine whether HLA-B allotypes had an impact on clinical outcome, we performed univariate and multivariate Cox regression analyses of leukemia-free survival (LFS) for all alleles with an allele frequency of > 10% in the cohort." (PMID 37597015, 2023). "Moreover, HLA-B*40:02 allele frequency in leukemia patients was lower than in the general population." (PMID 35626230, 2022). "A total of 36 different HLA-B*07:02-restricted O-GlcNAcylated peptides were identified on various primary leukemia samples." (PMID 36017166, 2022). "The HLA-B8 restricted mHag UTY and the HLA-B*2705 restricted mHag DDX3Y are described to be expressed on leukemia stem cells." (PMID 25774796, 2015). "Results were confirmed using HLA-B RFQ analysis and leukemia-associated aberrant immunophenotype (LAIP) based cell sort." (PMID 24860670, 2014). "Finally, HLA-B and -C are suggested to be involved in tumorigenesis of different non-leukemia cancer types." (PMID 38023151, 2023). "This indicates that HLA-B −21M polymorphism is unlikely to affect leukemia susceptibility in Chinese Southern Han." (PMID 31379844, 2019). "The data indicate a statistically significant correlation between these HLA alleles and various forms of leukemia in Moroccan patients, suggesting that HLA-B*44, HLA-DRB1*01, and HLA-DRB1*13 may either predispose persons to or confer protection against leukemia." (PMID 40508101, 2025). "Additionally, O-GlcNAc-modified peptides associated with MHC-I (HLA-B*07:02) were identified as potential neoantigens in leukemia, suggesting that despite a low TMB, leukemias could still be highly immunogenic." (PMID 39713021, 2024). "We have identified three distinct HLA types of NPMc+ AML patients which differ in the disease incidence and evolution: (i) in patients expressing HLA-B ́40, the presumed positive impact of the immune response occurrs mainly in the early phase of the disease and may prevent leukemia development." (PMID 30557403, 2018). "HLA-B*44 heralded impaired LFS (leukemia-free survival) and overall survival (OS), but the negative association with outcome was not shared across alleles of the HLA-B44 supertype." (PMID 37597015, 2023). "Importantly, some of these genes have already been reported in relation to CML (e.g., AURKB, AZU1, HLA-B, HLA-DMB, PF4) and others have been found to play important roles in different leukemias (e.g., CDCA3, RPL18A, PRG3, TLX3)." (PMID 35008420, 2022). "Since this could not be attributed to predominant donor chimerism, indicated by only diminished sequence signals for the donors specific HLA-B*08:01, an HLA-LOH in the leukemia cells was suspected." (PMID 24860670, 2014).